ENSG00000238761
Synonyms: LOC124904812
Gene: Small nucleolar RNA gene on chromosome 1 (112,371,004 to 112,371,107, forward strand). Ensembl gene ENSG00000238761.
Gene Ontology:
Biological process: RNA processing
Cellular component: nucleolus
Homologues: Paralogues in human: SNORD13P3 (81% identical), SNORD13P1 (80% identical), SNORD13 (79% identical), SNORD13D (77% identical), SNORD13E (76% identical).